ZNF333 (zinc finger protein 333)
Description:
May be involved in transcriptional regulation.
Synonyms: KIAA1806
Tractability: No criterion of Open Targets' tractability assessment is met for any kind of drug.
Gene: Protein-coding gene on chromosome 19 (14,689,801 to 14,733,746, forward strand). Ensembl gene ENSG00000160961.
Subcellular location: Nucleus
Subcellular location (Human Protein Atlas): Nucleoplasm; Cytosol
Pathways (Reactome):
Gene expression (Transcription): Generic Transcription Pathway
Gene Ontology:
Molecular function: protein binding; DNA-binding transcription factor activity, RNA polymerase II-specific; RNA polymerase II cis-regulatory region sequence-specific DNA binding
Biological process: regulation of transcription by RNA polymerase II; regulation of DNA-templated transcription
Cellular component: nucleus
Genetic constraint (gnomAD): Loss-of-function variants: 59 observed, 76.3 expected, observed/expected ratio (o/e) 0.77, 90% interval 0.63 to 0.96. The upper end of that interval is the gene's LOEUF score, 0.96, which puts it in group 4 of 6, group 1 being the genes least tolerant of losing a copy. Missense variants: 696 observed, 842 expected, observed/expected ratio (o/e) 0.83, 90% interval 0.78 to 0.88. Synonymous variants: 278 observed, 314.6 expected, observed/expected ratio (o/e) 0.88, 90% interval 0.8 to 0.98.
Homologues: Orthologues: chimpanzee ZNF333 (99% identical), macaque ZNF333 (94% identical), pig ZNF333 (74% identical), dog ZNF333 (66% identical). Paralogues in human: ZKSCAN7 (32% identical), ZNF287 (31% identical), ZNF426 (31% identical), ZNF527 (30% identical), ZNF34 (29% identical), ZNF214 (28% identical), ZNF17 (28% identical), ZNF852 (28% identical), ZNF285 (27% identical), ZNF136 (27% identical), ZNF627 (27% identical), ZNF530 (26% identical), and 38 more.
Diseases named in the same sentence as ZNF333 in open-access papers:
ZNF333 is named in the same sentence as 3 diseases in open-access papers, as found by Europe PMC text mining. Sharing a sentence is not in itself a finding about the gene and the disease.
ZNF333 shares sentences with these, for which no sentence is quoted: breast tumor (1 paper); cardiovascular disease (1); diabetes (1).